CBX8 (chromobox 8)
Diseases named in the same sentence as CBX8 in open-access papers (continued):
Sharing a sentence is not in itself a finding about the gene and the disease.
ovarian carcinoma (7 papers, 2020 to 2025). A malignant neoplasm originating from the surface ovarian epithelium. "It is critical to investigate CBX8 expression and its relationship with clinicopathological characteristics in liver hepatocellular carcinoma (LIHC), kidney renal clear cell carcinoma (KIRC), and ovarian cancer (OV) to investigate CBX8's potential diagnostic and prognostic values." (PMID 35813444, 2022). "In ovarian cancer (OC), CBX8 promotes tumor growth and metastasis by interacting with acetyltransferases inhibitor subunit SET." (PMID 40175347, 2025). "Evaluating the effect of CBX8 KD on ovarian carcinoma growth and metastasis using subcutaneous and abdominal metastatic xenograft mouse models." (PMID 40175347, 2025). "Nevertheless, the prognostic value of the other five CBXs family members for predicting OS and PFS in ovarian cancer patients was either irrelevant (CBX5 and CBX8) or inconsistent (CBX4, CBX6, and CBX7)." (PMID 35155439, 2022). "As for CBX8, the current data display that a high expression pattern was observed in most cancers, such as CRC, BC, ovarian cancer and other cancer." (PMID 36140750, 2022). "However, the results showed that the prognostic significance of CBX4-8 mRNA expression for predicting OS and PFS in all patients with ovarian cancer was inconsistent (CBX4, CBX6 and CBX7) or irrelevant (CBX5 and CBX8)." (PMID 32742466, 2020).
liver cancer (6 papers, 2018 to 2025). An epithelial or non-epithelial malignant neoplasm that arises from the liver. "In liver cancer, YBX1 interacts with CBX8 to regulate the cell cycle and promote the proliferation of liver cancer cells." (PMID 40799245, 2025). "Accordingly, higher mRNA expression of CBX8 was also significantly related with shorter OS of liver cancers patients and was an independent prognostic factor for shorter OS of liver cancer patients." (PMID 30481161, 2018). "Furthermore, high expression of CBX8 was dramatically correlated with shorter OS in patients with liver cancer." (PMID 35464847, 2022). "Chris discovered CBX8 via the AKT/β-Catenin signaling pathway to affect liver cancer development." (PMID 35813444, 2022). "We further examined the expression of CBX8 in sorted primary EpCAM+ or CD133+ liver cancer cells." (PMID 30718464, 2019).
glioma (5 papers, 2013 to 2025). A benign or malignant brain and spinal cord tumor that arises from glial cells (astrocytes, oligodendrocytes, ependymal cells). "Next, we explored the effect of CBX7 and CBX8 on the proliferation capacity in these two glioma cells." (PMID 36034290, 2022). "The overexpression of CBX7 and underexpression of CBX8 significantly inhibited the proliferation and invasion of glioma cells in vivo and in vitro." (PMID 36034290, 2022). "CBX8 also presented a differential expression in glioma tissues, which exhibited a prognostic value for predicting glioma patients' survival." (PMID 36034290, 2022). "Our results suggested that CBX7 and CBX8 served as independent prognostic indicators that promoted the proliferation and invasion of glioma cells, providing a promising strategy for diagnosing and treating GBM." (PMID 36034290, 2022). "Next, based on the gene regulation technology using lentivirus transfection, we established two models of CBX7-upregulated expression and CBX8-downregulated expression in the U87 and U251 glioma cells, respectively." (PMID 36034290, 2022). "Then, using the CCK-8 assay, we found that CBX8 knockdown suppressed the proliferation of glioma cells with siCBX8." (PMID 35210369, 2022). "The result indicated that overexpressed CBX7 and downregulated CBX8 in glioma cells showed a decreased expression of MMP2 and MMP9 and displayed significantly lower invasion abilities in scratch wound-healing assay when compared to the control." (PMID 36034290, 2022). "In each group, CBX8 expression was significantly higher in tumor tissues than in normal tissues, and glioma patients with higher CBX8 expression displayed significant poorer overall survival than those with lower CBX8 expression." (PMID 33251331, 2020). "Functional assays confirmed CBX8’s role in promoting glioma cell proliferation." (PMID 40565099, 2025). "Finally, we confirmed the roles of CBX7 and CBX8 in the proliferation and invasion of glioma cells in vivo and in vitro experiments, which provided a promising strategy for GBM treatments." (PMID 36034290, 2022). "Further cell experiment results supported that CBX8 promoted the proliferation of glioma cells." (PMID 35210369, 2022). "Moreover, through CCK8 assay and transient transfection assay, we found that CBX8 promoted the proliferation of glioma cells." (PMID 35210369, 2022). "Besides, through CCK8 assay and transient transfection assay, we found that CBX8 promoted the proliferation of glioma cells." (PMID 35210369, 2022). "Furthermore, we explored and confirmed the roles of CBX7 and CBX8 in the proliferation and invasion of glioma cells in vivo and in vitro." (PMID 36034290, 2022). "In our studies, we confirmed the same effect of CBX8 on the glioma cells in vivo and in vitro." (PMID 36034290, 2022). "CBX1-3, CBX5, and CBX8 were significantly elevated in the brain and CNS cancers." (PMID 36034290, 2022). "They found that the higher expression of CBX8 in glioma indicated a more dismal prognosis of GBM due to its positive role in the propagation and invasion of glioma cells." (PMID 36034290, 2022). "To investigate the role of CBX8 in glioma cell growth, we used a CCK-8 assay to prove the effect of knockdown of CBX8 on cell proliferation." (PMID 35210369, 2022). "However, in a cohort which includes low grade gliomas, significant survival benefits were observed for patients with low EZH2, PHF19, CBX8 and PHC2 expression, and high CBX7, CBX6, RYBP and EZH1 expression." (PMID 24260522, 2013).
lymph node metastasis (4 papers, 2021 to 2022). "Our study showed that patients with high NAT CBX8 were associated with a worse stage, tumor invasion, lymph node metastasis, distant metastasis, and poor DFS and OS, suggesting that CRC patients with high NAT CBX8 are potential candidates for CBX8-targeted treatment." (PMID 35681547, 2022). "TAGA and GEO database analysis showed that the survival rate of patients with high expression of CBX8 tumors was lower.TCGA database analysis further showed that the survival rate of patients with lymph node metastasis was shorter than that of patients without lymph node metastasis." (PMID 35814427, 2022).
acute myeloid leukemia (3 papers, 2021 to 2024). Acute myeloid leukemia (AML) is a group of neoplasms arising from precursor cells committed to the myeloid cell-line differentiation. "Additionally, we evaluated GeneCompass by in silico deleting more transcription factors (TFs) in various cell types of different species, i.e., STAT1 on human PBMC cells, SMARCA4 on human acute myeloid leukemia cells, CBX8 on mouse embryonic stem cells, and MTA2 on mouse colonic epithelium cells." (PMID 39375485, 2024).
cervical cancer (3 papers, 2021 to 2025). A primary or metastatic malignant neoplasm involving the cervix. "CircRNA8924 acts as a sponge for miR-518d-5p and influences the chromobox 8 (CBX8) gene expression closely associated with histogenesis, invasion and metastasis, and prognosis of cervical cancer." (PMID 33803232, 2021). "We found that CBX2, CBX4, and CBX8 presented notably increased expression, whereas PHC2, CBX6, and CBX7 presented decreased expression in cervical cancers." (PMID 39793896, 2025). "In GSE63514, increased expression of CBX2, but not CBX4 or CBX8, was detected in cervical cancer patients compared with normal controls, and cervical precancerous lesions were observed." (PMID 39793896, 2025).
esophageal cancer (3 papers, 2021 to 2022). A primary or metastatic malignant neoplasm involving the esophagus. "In vitro experiments have demonstrated that knockout of CBX8 can inhibit the clone formation of esophageal cancer cells, thus reducing the size and weight of transplanted tumors in nude mice." (PMID 34449496, 2021).
lymphoma (3 papers, 2021 to 2024). A malignant (clonal) proliferation of B- lymphocytes or T- lymphocytes which involves the lymph nodes, bone marrow and/or extranodal sites. "In agreement, knockdown of CBX8 in lymphoma cells results into reduced proliferation and induced differentiation potential, indicating that CBX8 has oncogenic potential in lymphoma as well." (PMID 38426219, 2024). "Furthermore, enforced overexpression of CBX8 in lymphoma cells promotes proliferation and prevents apoptosis." (PMID 38426219, 2024). "Inhibition of CBX8 with UNC7040 prevents binding of CBX8 to H3K27me3‐covered loci, which leads to reduced cell growth of lymphoma cells." (PMID 38426219, 2024).
lung adenocarcinoma (2 papers, 2021 to 2022). A carcinoma that arises from the lung and is characterized by the presence of malignant glandular epithelial cells. "We speculated that the high expression of CBX8 in lung adenocarcinoma patients may increase the tumors sensitivity to radiotherapy and chemotherapy." (PMID 34966411, 2021).
mesothelioma (2 papers, 2020 to 2021). A usually malignant and aggressive neoplasm of the mesothelium which is often associated with exposure to asbestos. "Amplification was the only CBX8 genetic alteration type for mesothelioma, uterine carcinosarcoma, UVM, LGG, pheochromocytoma and paraganglioma (PCPG), THYM and PAAD." (PMID 34567093, 2021).
Neuroendocrine tumor (2 papers, 2015 to 2022). "In addition, overabundance of CBX6 and CBX8 transcripts was also observed in neuroendocrine tumor lines (P < 0.05, Mann-Whitney U test), consistent with our previous findings." (PMID 25859291, 2015).
pancreatic cancer (2 papers, 2021 to 2022). "It is worth noting that the mRNA levels of CBX1, CBX3, CBX5 and CBX8 were elevated in pancreatic cancer tissues compared with non-malignant pancreatic tissues." (PMID 35637952, 2022).
prostate carcinoma (2 papers, 2016 to 2025). A carcinoma that arises from epithelial cells of the prostate gland. "MiR-375-mediated repression of CBX7 was accompanied by increased expression of its homolog CBX8 and activated transcriptional programs linked to malignant progression in prostate cancer cells." (PMID 27449098, 2016). "To investigate whether CBX7 loss leads to upregulation of CBX8 in prostate cancer cells, we transfected LNCaP cells with siRNAs against CBX7, thereby emulating the effect of miR-375 de-repression." (PMID 27449098, 2016). "MiR-375-mediated repression of CBX7 leads to higher levels of CBX8 in prostate cancer cells." (PMID 27449098, 2016). "Then we further clarified the expression of CBX family members in prostate cancer, which result showed that CBX5, CBX6 and CBX7 were significantly down-regulated in prostate cancer tissues, while CBX3, CBX2, CBX4 and CBX8 was notably up-regulated." (PMID 40861818, 2025).
alcohol abuse (1 paper, 2019). The use of alcoholic beverages to excess, either on individual occasions ("binge drinking") or as a regular practice. "While HCC is often developed from an infection of hepatitis virus or alcohol abuse, CBX8 expression was also potent in clarifying prognosis in patients with viral or toxic pathogeny." (PMID 31495785, 2019).
brain tumors (1 paper, 2020). "Considering the CBX8 expression profile and clinical implications, we further examined its expression in brain tumors (data published in Tang et al24)." (PMID 33251331, 2020).
endometrial tumors (1 paper, 2022). "As for CBX1 and CBX2—we observed positive association with cancer stemness in liver, lung and endometrial tumors, while CBX4, CBX5, CBX6, and CBX8 exhibit rather weak correlation with cancer stemness in a tumor-specific manner." (PMID 36361869, 2022).
esophageal adenocarcinoma (1 paper, 2022). A malignant tumor with glandular differentiation arising predominantly from Barrett mucosa in the lower third of the esophagus. "Furthermore, the high expression of CBX8 in Esophageal Adenocarcinoma patients was significantly related to poor OS, indicating CBX8 involved in the tumorigenesis of ESCA." (PMID 35464847, 2022). "The overexpression of CBX3 (HR = 3.12, p = 0.00028) and CBX8 (HR = 2.27, p = 0.035) mRNAs in esophageal adenocarcinoma patients were significantly correlated with shorter OS, whereas the overexpression of CBX7 mRNA (HR = 0.48, p = 0.039) was significantly correlated with longer OS." (PMID 35464847, 2022).
gastric cancer (1 paper, 2022). A primary or metastatic malignant neoplasm involving the stomach. "Univariate and multivariate regression analyses revealed that CBX3, CBX8, age, gender, pT stage, pN stage, and pM stage were independent factors for the prognosis of gastric cancer patients." (PMID 35969177, 2022). "A prognostic gene model based on five CBX genes (CBX1, CBX2, CBX3, CBX7, and CBX8) predicted the overall survival of gastric cancer patients." (PMID 35969177, 2022). "Moreover, we found a prognostic CBXs model comprising five genes (CBX1, CBX2, CBX3, CBX7, and CBX8) for gastric cancer patients." (PMID 35969177, 2022). "In addition, the RNA-seq data revealed that the mRNA expression levels of CBX1 (HR=1.61, p = 0.02) and CBX8 (HR = 0.62, p = 0.0048) significantly correlated with clinical outcomes in gastric cancer." (PMID 35969177, 2022).
laryngeal squamous cell carcinoma (1 paper, 2022). A squamous cell carcinoma that arises from the larynx. "In this study, we detected the expression of chromobox protein homolog 8 (CBX8) in laryngeal squamous cell carcinoma (LSCC) and its influence on the occurrence and progression of LSCC." (PMID 35814427, 2022).
metastatic cancers (1 paper, 2020). A carcinoma which has spread from the original site of growth to another anatomic site. "Therefore, CBX8 may be a novel therapeutic target to treat metastatic cancers." (PMID 33251331, 2020).
metastatic disease (1 paper, 2019). "Our results demonstrated that CBX8 regulates these two essential characteristics of metastatic disease and that CBX8-induced processes are reversible with the suppression of CBX8 expression." (PMID 30718464, 2019). "Our study describes a novel function of CBX8 in HCC metastasis of promoting two essential characteristics of metastatic disease in HCCs: EMT and stemness." (PMID 30718464, 2019).
myeloid leukemia (1 paper, 2024). A clonal proliferation of myeloid cells and their precursors in the bone marrow, peripheral blood, and spleen. "Although CBX8 was found as a PCGF1 interactor in myeloid leukemia cells, molecular evidence of CBX8 as being an active member in the PRC1.1 complex in leukemic cells is lacking." (PMID 38426219, 2024).
neuroblastoma (1 paper, 2025). Neuroblastoma (NB) is the most common solid, extracranial childhood tumor. "Downregulation of repair proteins FEN1 and CBX8 may cause impaired DSB repair that leads to enhanced DSB accumulation, increasing apoptosis in stage 4S neuroblastoma." (PMID 41189817, 2025).
osteoarthritis (1 paper, 2022). A noninflammatory degenerative joint disease occurring chiefly in older persons, characterized by degeneration of the articular cartilage, hypertrophy of bone at the margins and changes in the synovial membrane. "CBX8 participates in IDD, and CBX4 exhibits therapeutic potential in treating degenerative diseases such as osteoarthritis." (PMID 35880565, 2022). "CBX8 participates in the ECM metabolism through regulating cell proliferation and cell cycle in NP cells, another CBX protein member, CBX4, could alleviate osteoarthritis by restraining human mesenchymal stem cell senescence." (PMID 35880565, 2022).
osteosarcoma (1 paper, 2020). A usually aggressive malignant bone-forming mesenchymal neoplasm, predominantly affecting adolescents and young adults. "We found that CBX4 and CBX8, but not CBX2 or CBX6, was overexpressed in all 16 osteosarcoma tissues compared with the 4 normal tissues." (PMID 32111827, 2020).
rectal adenocarcinoma (1 paper, 2021). "Consistent with the Oncomine database, CBX1-5 and CBX8 transcripts in colon and rectal adenocarcinoma tissues were higher than in normal tissues." (PMID 34321009, 2021).
rectal cancer (1 paper, 2020). A primary or metastatic malignant neoplasm that affects the rectum. "However, CBX8 expression was is closely tied to only with the infiltration of B cells and CD4+ T cells in rectal cancer." (PMID 33014884, 2020).
renal cell carcinoma (1 paper, 2022). "In this study, we performed bioinformatic analysis to show that CBX7 and CBX6 functioned as protective factors with hazard ratios (HRs) less than 1 but CBX8 and CBX4 functioned as risk factors with HRs greater than 1 in renal cell carcinoma." (PMID 35342353, 2022).
sarcoidosis (1 paper, 2022). Sarcoidosis is a multisystemic disorder of unknown cause characterized by the formation of immune granulomas in involved organs. "The TLE3 and CBX8 PLS-DA models were further parsed to identify target genes in the MAM cell death subnetwork most likely associated with the characteristic imbalance of PBMC proportions observed in sarcoidosis." (PMID 36311769, 2022). "Therefore, aberrant CBX8 regulatory activity may contribute to the dysregulated immune response observed in sarcoidosis as a result of epigenetic modifications of immune cell progenitors in addition to functional changes within PBMCs." (PMID 36311769, 2022). "Selectively targeting and modulating CBX8 and TLE3 activity may represent a promising novel strategy for management of sarcoidosis." (PMID 36311769, 2022).
urothelial carcinoma (1 paper, 2021). A malignant neoplasm derived from the transitional epithelium of the urinary tract (urinary bladder, ureter, urethra, or renal pelvis). "Results of our study suggested that high expression of CBX8 played a critical oncogenic role in the aggressiveness of urothelial carcinoma cells of the bladder by promoting cancer cell proliferation." (PMID 33731128, 2021).